TNF (tumor necrosis factor)
Diseases named in the same sentence as TNF in open-access papers (continued):
Sharing a sentence is not in itself a finding about the gene and the disease.
infection (continued). "Meanwhile, GL or GM pre-infection treatments significantly (P < 0.05) decreased ST-induced pro-inflammatory cytokine (IFN-γ, TNF-α, and IL-6) expression in both spleen and liver and increased (P < 0.05) anti-inflammatory cytokine IL-10 secretion in spleen." (PMID 34239908, 2021). "The TNF-α expression significantly increases during the initial stages of SARS-CoV-2 infection and boosting the expression throughout the infection." (PMID 34576032, 2021). "It is unclear why TNFα did reduce viral spike protein load in endothelial cells and limited information is available regarding the effects of TNFα on SARS-CoV-2 virus entry and infection rate." (PMID 34224022, 2021). "Previous experimental infection reported that IFN-γ, TNF-α, and iNOS showed increased expressions among the lymph node granulomas of BCG vaccinated cattle compared to non-vaccinated." (PMID 34604367, 2021). "At early time points of C. albicans infection, Trim31−/− mice showed significantly reduced secretion of IL-6, TNF-α, IL-12, CXCL1, and CXCL2 in their serum at 24 h post-infection as compared with Trim31+/+ mice." (PMID 34362877, 2021). "TNF-α and IFN-γ levels increased in the infected control group, reaching peak values on the 7th day after infection, and then gradually decreased to pre-infection levels." (PMID 33717108, 2021). "Then, knockdown or overexpression NARL also can significantly inhibit or promote the expression levels of TNF-α, MX1, and ISG15 upon SCRV infection." (PMID 33581111, 2021). "Infection was accompanied by progressive upregulation of proinflammatory cytokines such as IL6, IL1B and TNF, consistent with initiation of an NF-KB-dependent inflammatory response." (PMID 34876592, 2021). "Biological pathway analysis showed that HSPCs are producing proinflammatory cytokines, such as TNF-α and IL-6, in response to the PCA2 infection and especially after the ATCC 26555 secondary infection." (PMID 34975887, 2021). "Signals from DCs, such as TNF-α, recruit NK cells, which are crucial in restricting DENV replication and pathogenesis during the early stages of infection by IFN production." (PMID 34696397, 2021). "At the moment of infection, the promastigotes encountered an environment of high TGF-β gene expression and intermediary basal TNF, IL-6, and IL-4 gene expressions." (PMID 34276650, 2021). "At 48 h post infection, high percentages of cell death were again found for the DENV2-infected and the TNF-α plus DENV2 treated cells, with 39.72% and 67.58%, respectively." (PMID 34696472, 2021). "Several MMPs have been shown to cleave and modulate the functions of cytokines and chemokines such as IFN-γ, IL-1β, TNF-α, CXCL-8 and CCL-7, thereby regulating chemokine gradients and leukocyte recruitment to the site of infection." (PMID 35095865, 2021). "(F) RT-PCR analysis of IFNB1, IFIT2, IFIT1, TNF, IL6, and CCL20 mRNA levels in HEK293T cells transfected with HA-Ev or HA-RTN3 followed by infection with VSV-eGFP (MOI = 1) at the indicated timepoints." (PMID 34313226, 2021). "Next, we defined proinflammatory macrophages as cells expressing high levels of CCL2 and CCL3, chemokines involved in recruitment of adaptive and innate cells to sites of infection, and which were also characterized by the expression IL6, IL1B, and TNF." (PMID 33622974, 2021). "Although this was the case, the noticeable decreases in IL-1β, IL-2, IL-4, IL-12, IL-13, RANTES, TNF-α, and GRO-α observed in patients with lethal SARS-CoV-2 infection suggest that lethal infection results in an exhausted immune response." (PMID 33472985, 2021). "In this study, the levels of pro-inflammatory cytokines, including IL-1β, IL-6, TNF-α and IFN-γ, were elevated after infection, suggesting the innate immunity was activated by PRV." (PMID 34275451, 2021). "One of the major proinflammatory cytokines is tumor necrosis factor (TNF), which induces a strong response and stimulates the recruitment of immune cells to sites of infection or damaged tissue." (PMID 33808578, 2021).
infection (continued). "After infection with E. chaffeensis, MIP-2 (CXCL2) and TNF mRNA induction in murine bone marrow derived macrophages was MyD88-dependent, but did not require TLR2 or TLR4." (PMID 33747981, 2021). "Our investigation showed that the increased levels of TNF-α, IL-6, and IL-β in LPS-induced RAW 264.7 were inverted after the infection with miR-31-5p mimic." (PMID 33710444, 2021). "TNF-α, IFN-β are two important anti-infection factors in body immunity, and were therefore chosen to evaluate the immune status." (PMID 34737359, 2021). "Nlrp3−/− mice infected with F. tularensis LVS had significantly higher levels of IL-1β, IL-6, IL-12p40, G-CSF, GM-CSF, TNF-α, and RANTES as compared to the wild-type mice on day 3 post-infection." (PMID 34690967, 2021). "Neutrophil recruitment in the blood and at infection sites is orchestrated by chemotactic cytokines/chemokines, including GM-CSF, CXCL1/2, TNF-α, and IL-6." (PMID 34899755, 2021). "After 48 h of infection with K. oxytoca AD3, the levels of IL-6 and TNF-α in the thymus, lung, spleen, kidney, and liver of mice increased significantly, while IL-10 decreased significantly, which was effectively alleviated via phage therapy." (PMID 34925270, 2021). "Furthermore, high levels of TNF-α increase the expression of vascular endothelial adhesion molecules and increase the stimulation of endothelial cells and macrophages, which may lead to better infection resolution." (PMID 34732154, 2021). "After 8 h post-infection, the production of pro-inflammatory cytokines and chemokines, including IL-6, IFN-γ, TNF-α, and MCP-1, was pronounced in the plasma, which is associated with the septic symptoms." (PMID 34681611, 2021). "After infection by T. cruzi, peritoneal MΦ produced IL-10, TGFβ, TNFα, and VEGF at all of the times evaluated post-infection." (PMID 34832600, 2021). "For instance, when tested in a human whole blood ex vivo model of infection, a PIA-positive S. epidermidis strain (SE1457) induced lower levels of TNF-α, IL-6, IFN-γ production than its PIA-negative isogenic mutant (M10)." (PMID 34576742, 2021). "Per bin, the intron counts of the infection-induced genes IFIT2, OAS2, CCL5, IL6, NFKBIA, and TNF are shown, along with ATXN10 as control." (PMID 33585804, 2021). "Patients who succumbed to infection produced decreased IL-2, IL-4, IL-12, RANTES, tumor necrosis factor alpha (TNF-α), GRO-α, and MIP-1α relative to patients who survived infection." (PMID 33472985, 2021). "In fact, best correlates of protection for infections with other intracellular pathogens have been multifunctional CD4+ T cells, capable of producing IFN-γ, TNF-α and IL-2 simultaneously." (PMID 34451970, 2021). "We observed an increase of the concentration of IL-1β, TNF-α and MPO during the progression of the infection, which positively correlated with the concentration of PTX3 (P < 0.0001, P = 0.0018, P = 0.0139, respectively)." (PMID 34093560, 2021). "As expected, MVA-infection strongly induced secretion of type 1 interferons (IFN-I) and the IFN-stimulated gene products CXCL10 and CCL5 in macrophages, as well as IL-6, TNF, and GM-CSF." (PMID 34711816, 2021). "Myeloid KLF4 KO mice showed reduced levels of TNF-α, KC and IL-1β and increased levels of IL-10 in BALF and plasma after infection with S. pneumoniae." (PMID 34589087, 2021). "Naïve macrophages can be activated either classically into a proinflammatory M1 phenotype by IFNγ, TNF-α, and TLR ligands to defend against infection or into an anti-inflammatory M2 phenotype by IL-4 and IL-13 to aid in healing." (PMID 34539613, 2021). "These cells are recruited to the site of infection and are capable of producing various cytokines, including interferon gamma (IFN-γ) and tumor necrosis factor alpha (TNF-α)." (PMID 34604367, 2021). "But currently, there are no recognized standard biomarkers to assess SCI levels alone, and SCI is typically measured by combining biomarkers of acute inflammation and infection, e.g., CRP, IL-6, and TNFα." (PMID 34925360, 2021).
infection (continued). "We used three different inflammatory stimuli, such as LPS from P. aeruginosa, mimicking the infection, and IL-1β/H2O2 and IL-1β/TNF-α, resembling the inflammatory milieu." (PMID 34440900, 2021). "For CQ treatment, levels of pro-inflammatory cytokines TNF-α, IFN-γ, IL-10 and IL-4 were also decreased significantly after infection (to 12.0, 25.0, 9.0, and 1.5 times that in controls, respectively)." (PMID 33803419, 2021). "Expression of IL-6, IL-18, TNF-α, IFN-γ, and CCL2 increase within 24 h of infection of P815 cells with either a H1N1, H5N1, or H7N2 strain of IAV." (PMID 33680987, 2021). "Compared to sham treatment, RV-C15 infection significantly increased mRNA expression of IFN-γ, CXCL10, CXCL1, CXCL2, TNF-α, IL-12, IL-25, IL-13 and IL-5." (PMID 33968043, 2021). "Infection with LT2 increased levels of IL-8, TNF-α, and IL-10 in the intestine and plasma, and BB12 mildly downregulated them compared to LT2 alone." (PMID 33670419, 2021). "In fact, secretion of cytokines TNF-α and IFN-γ tended to be higher when the host controlled the infection and that of IL-4 and TGF- β when the infection remained uncontrolled." (PMID 33668671, 2021). "(A–C) Serum levels of inflammatory cytokines IL-1β (A), TNFα (B), and IL-6 (C) of young (6 months old) and old (24 months old) infected mice on day 8 post (PFU 7e2) infection." (PMID 34151773, 2021). "Previous studies have shown the importance of macrophage TLR2 activation for the secretion of IL-1β, IL-6, TNF-α, IFN-β during the infection with L.m." (PMID 34194428, 2021). "In concordance with the transcript data, release of TNF, IL-8, and CXCL5 was consistent across all three infection conditions." (PMID 34006652, 2021). "Colonization with either strain resulted in increased concentrations of nitric oxide and TNF in the colonic biopsies (p < .01–0.001), which also held true for colonic IFN-γ secretion upon WT strain or pepP complemented strain infection (p < .001)." (PMID 32584649, 2020). "Our results show that the relative transcription levels of IL-17A, IL-22, IL-6, IL-1β, IFN-γ, and TNF-α increased at 5 and 12 days post H9N2 AIV infection, and these results are consistent with our previous research results and other reports." (PMID 33294434, 2020). "As expected, mice infected with Cr had increased colonic tissue expression of several cytokines associated with a pro-inflammatory Th1/Th17 immune response including IL-17A, IL-22, IL-6, IL-1β, TNF-α, and IFN-γ on day 12 after infection." (PMID 33076301, 2020). "Among influenza A/H3N2-infected patients, stimulation with H1N1 elicited a significant increase in IL2+, TNFα+ and polyfunctional CD4+ T-cells, as seen with stimulation with H3N2 suggesting that natural infection does result in heterosubtypic immunity." (PMID 32572168, 2020). "At three days after treatment, TNF-α, IL-6, and MCP-1 in the serum of the amphenmulin treatment group were significantly decreased than those of the infection group (p < 0.05)." (PMID 32079232, 2020). "In general, H3N2 and H5N1 infection induced IFN-α, TNF-α, MCP-1 (CCL-2), IL-1β, and IL-6 responses in ANP32B+/+ mice were reduced in ANP32B−/− mice, particularly 3 days post infection." (PMID 32231671, 2020). "Cr infection triggered an increase in serum cytokines in Cr-infected mice fed the control diet, especially increasing the levels of IL17, TNF-α, IL12 (p40, p70) and G-CSF." (PMID 33076301, 2020). "After infection with MGAS5005, MGAS315, or MGAS6180, the levels of three such cytokines (IFN-γ, TNF-α, and IL-1β), which are important for effective innate immunity against GAS, increased in SseM1-immunized mice compared with control mice." (PMID 32308652, 2020). "Some studies in experimental models and human infection with leishmania parasites have demonstrated that CD8+ T cells play a vital role in immune protection through cytokine production (IFN-γ, TNF-α) as well as their cytotoxic activity." (PMID 32656269, 2020).
infection (continued). "In blood, we observed an increase in cells expressing the antiviral cytokines, TNF-α and IFN-γ, upon vaccination and infection compared to pre-levels, suggesting better functionality of both cell populations." (PMID 32572140, 2020). "Specifically, attenuation in the ΔcomR group was the most obvious as the concentrations of TNF-a, IL-1β, and MCP-1 were all significantly reduced at 3, 6, and 9 h post-infection." (PMID 32825733, 2020). "On the contrary, nicotine in CD active smokers associated with bacterial infection induce M1-macrophage polarization, upregulation of iNOS, IL-6, and TNF-α, downregulation in CD206, IL-10, decrease in caspase-3 activity, and increase in infection burden." (PMID 32370298, 2020). "We next analyzed CD8 T cell responses and did not observe significant differences for IFN-γ-expressing CD8 T cells and TNF-α–expressing CD8 T cells between WT and IL16 KO mice at day 16 post-infection." (PMID 32735617, 2020). "The frequencies of splenic CD4+ T cells expressing IFN-γ, IL-10 and TNF-α were found similar in vaccinated and control mice, whereas a reduction of CD4+IL-4+ cells frequency was observed upon infection in vaccinated mice." (PMID 32040500, 2020). "Characterization of SARS-CoV-specific memory T cells from recovered individuals 4 years after infection indicated that the majority of memory CD8+ T cells produced IFN-γ, whereas memory CD4+ T cells produced IFN-γ, IL-2, or TNF-α." (PMID 33013871, 2020). "Once infected, the host immune system generates a potent inflammatory response that includes cytokines such as IFN-γ and tumor necrosis factor (TNF), which act synergistically and promote parasitic load control during the acute phase of infection." (PMID 33347472, 2020). "We evaluated infection index, hydrogen peroxide production, nitric oxide generation and levels of the immunomodulatory IL-12 and TGF-β, and the level of the inflammatory TNF-α." (PMID 32640562, 2020). "Therefore, MDMA-induced TNF-α reduction may affect host resistance to infection." (PMID 32922492, 2020). "We measured the protein levels of NF-kB, RAGE, TNFα, and IL-1β in lung tissue and we found that positive expression levels were induced by the A/H5N1 lethal infection (mock-treated groups)." (PMID 33176722, 2020). "Neutrophils are known to secrete cytokines and chemokines in response to infection neutrophils infected with H5N1 subtypes induced a trend of stronger gene transcription of TNF-α, IFN-β, CXCL10 and MIP-1α than that of H1N1 subtypes." (PMID 32576265, 2020). "Lactoferrin significantly increased TNF-α production by differentiated THP-1 cells and blood monocytes after Bt infection." (PMID 32764765, 2020). "Reduced levels of TNF and IL-6 by anti-EDII-cEDIII Ab treatment were observed in the liver during infection of various serotypes of DENV, excluding DENV3." (PMID 32075300, 2020). "NF-κB, TNF-α, and CXCL2 signaling are potential targets of XBJ and C0127s in infection-induced cardiac dysfunction." (PMID 33986658, 2020). "The first, 5 days of infection showed peak levels of IL-1RA, MCP-1, MIP-1β and TNF-α; the second 5 days had peak levels of GM-CSF, IL-1β, IL-6, IL-8, IL-9, IP-10 and MIP-1α; VEGF peaked at 11–15 days." (PMID 32264832, 2020). "Using Luminex multiplex immunoassay, we measured cell culture supernatant fluid levels of the cytokines TNF-α, IL-1β, IL-6, IL-10, RANTES, and IL-8 at 6 h and 24 h following infection." (PMID 32994292, 2020). "In agreement with the gene expression data, infection with Mtb WT significantly increased the secretion of IFN-α, TNF-α, IL-8, MCP-1, IL-1-α, IL-6 and MIP1-α and MIP1-β." (PMID 32938685, 2020). "Comparison of cytokine production from the BALF of mice treated with 80 μg anti-TNFR1 or anti-TNFR2 prior to infection with RSV yielded similar reductions, with the exception of TNF-α." (PMID 33080861, 2020).
infection (continued). "The mRNA levels of IL1β, IL6, TNF-α and IFN-β in porcine intestinal epithelial cells infected with SDSX16-P10 strain were much lower than SDSX16-P75 at 18 h post-infection (hpi)." (PMID 32244640, 2020). "In addition to reducing the bioburden in wound tissue, AMPs can modulate the immune response by stimulating leukocyte recruitment to the site of infection and the production of immune mediators GM-CSF, and inhibit S. aureus-evoked expression of the pro-inflammatory cytokines of TNF-α and IL-6." (PMID 33042031, 2020). "However, it remained open whether TNF-α was induced at earlier time points after infection." (PMID 31947746, 2020). "In conclusion, we demonstrated that H. pylori regulates SOCS3 during early infection and that this process requires an intact T4SS system and TNFα-mediated activation of p38." (PMID 33023610, 2020). "In our study both mouse strains infected by T. cruzi SC2005 produced high levels of TNF-α and IFN-γ at 14 days of infection, correlating with the decrease of RBC and Hgb." (PMID 33329529, 2020). "The infection promptly elicits secretion of gamma interferon (IFN-γ), tumor necrosis factor (TNF), interleukin-1 (IL-1), IL-2, and macrophage inflammatory protein; these cytokines have an antiviral activity and limit the amplification and spread of the virus." (PMID 33066100, 2020). "In fibroblasts the infection produces IFN-β, tumor necrosis factor-α (TNF-α), interleukin-4 (IL-4), IL-1-β, chemokine (C-C motif) ligand 2 (CCL2), and chemokine (C-C motif) ligand (CCL5)." (PMID 31979145, 2020). "In agreement with previous studies, the dysregulation observed in the severe group during the acute phase of the infection mainly comprised the upregulation of secreted inflammatory mediators, such as IL-8, MIP-1α, MIP-1β, M-CFS, MIF, and TNF-α." (PMID 32990499, 2020). "After infection monocytes are recruited to the spleen via CCR2 and differentiate into TNF/iNOS-producing CD11bint/CD11cint dendritic cells (TipDCs)." (PMID 32760383, 2020). "Changes in gene expression in the brains of infected animals is minimal at 2- and 4-days post infection with moderate increases in Interferon-inducible CXCL10, CXCL11, B2m, and STAT1, as well as pro-inflammatory TNF, IL-1b and C3." (PMID 32133008, 2020). "On the one hand, activation of T cells by antigens in vitro results in secretion of cytokines, especially Tumor Necrosis Factor (TNF)-α and Interferon (IFN)-γ, and initiates pro-inflammatory, anti-infection responses." (PMID 32235616, 2020). "At lower doses of infection, SPN:Ply-H elicited reduced secretion of TNF-α, IL-1β and IL-12 compared to SPNΔply." (PMID 33216805, 2020). "infection, whereas the corresponding early responding genes in SCC cells were IL10, IL1β, IL1α, TNF, CXCL10, CXCL1, HBEGF, IL6, and CSF3." (PMID 31912662, 2020). "Together with enhanced resistance to infection, ST2−/− produced greater levels of IFN-γ and TNF-α in the small intestine, compared to WT mice." (PMID 32353980, 2020). "The expression of genes related to Th1-related cytokines (TNF-α, IFN-γ, and IL-12p35) and Th17-related cytokines (IL-23 and IL-6) were significantly increased in canine PBMCs after 6 h post infection." (PMID 33520738, 2020). "On the other hand, C3H/He spleen showed an early response to infection, with high expression of TNF-α, TGF-β, IL-12, IFN-γ, and iNOS, suggesting a commitment of the spleen in the early response against infection." (PMID 32983013, 2020). "The role of the innate immune responses by eliciting the pro-inflammatory cytokines such as interferon γ (IFNγ), tumor necrosis factor α (TNFα) and interleukin-12 (IL12) during blood-stage infection was well documented." (PMID 32181014, 2020). "In infected T-bet−/− mice, the induction of TNF-α was maintained in CD4+ T cells, whereas infection resulted in enhanced Th17 responses, which were largely undetectable in infected WT mice." (PMID 32591391, 2020).